TNF (tumor necrosis factor)
Diseases named in the same sentence as TNF in open-access papers (continued):
Sharing a sentence is not in itself a finding about the gene and the disease.
Arthritis (continued). "Mechanically, the NDDS administration promoted Treg differentiation and decreased Th17 production, consequently reversing the ratio of Treg/Th17, and reducing the secretion of TNF-α in the sera, which facilitated to relieve the severity and progression of arthritis." (PMID 36714199, 2023). "TNF-α inhibitor treatment reverses this enhanced central nervous system activity in both mice and humans within 24 h, again, even before the clinical effects on arthritis are observed." (PMID 37568441, 2023). "In the CIA model, the dual blockade of TNF and IL-17 gave better results than either monotherapy and in the TNFα transgenic animal model of arthritis, as well as cartilage and bone damage, were better controlled with bi-specific antibodies (anti-TNFα and anti–IL-17A) than with monotherapies." (PMID 37035302, 2023). "Specifically, future studies ought to be evaluated through targeted anti-CD6 inhibitors in TNF-Tg mice, or through genetic ablation of CD6 by crossing CD6-KO with TNF-Tg cohorts, to investigate endpoints such as arthritis severity and IgG2b+ plasma cell accumulation in downstream PLNs." (PMID 37691918, 2023). "In addition to a TNF‐driven arthritis model, we also evaluated the importance of the microbiome for arthritis development in the IL‐1β‐dependent myeloid‐specific A20‐deficient (A20myel‐KO) mouse model of arthritis." (PMID 37694693, 2023). "In one case study, a T1D patient receiving anti-TNFα treatment (etanercept) for arthritis lost stable control of her blood glucose levels, where they were described as “erratic” and lead to severe hypoglycemic attacks without warning, having previously had stable control." (PMID 37483613, 2023). "Consequently, the anti-arthritic effect of the bispecific antibody became evident in the TNFα human transgenic arthritis model — hTNFtg (C57Bl6 background, Tg197 strain)." (PMID 37035302, 2023). "The results showed that miR-181a-5p could reduce the release of IL-1β, IL-6, TNF-α and iNOS inflammatory factors in cellular model of arthritis." (PMID 37587519, 2023). "Using two independent transgenic mouse arthritis models, either TNF‐ or IL‐1β dependent, we demonstrate that arthritis develops independently of the microbiota and intestinal inflammation, since both lines develop full‐blown articular inflammation under germ‐free conditions." (PMID 37694693, 2023). "The first data on the effects of anti-TNFα therapy were drawn from patients with arthritis who seemed to have no increased risk to develop new or recurrent cancer after exposure to anti-TNFα compared to patients without anti-TNFα therapy." (PMID 36672491, 2023). "Similarly, recent literature reported that Nec-1 significantly reduced the levels of TNF-α, IL-1β, and IL-6 and reduced the severity of arthritis in rats." (PMID 37446099, 2023). "These factors are important for the effectiveness of TNF inhibitors in the treatment of arthritis." (PMID 38144420, 2023). "Thus, targeting this pathway to evaluate the effects on TNF-Tg arthritis and lymphatic pathology is warranted." (PMID 37691918, 2023). "At the onset of arthritis, IL-8, TNF-α, and IL-23p19 mRNA expression was increased in AIA rats." (PMID 37280714, 2023). "In light of the effects of BSR/5-Loxin® on inflammatory mediators and enzymes in these studies on animal diseases, it is interesting that exogenously added SPMs reduced the levels of pro-inflammatory cytokines like TNF-α and IL-6 as well as of MMPs and nitric oxide in comparable arthritis models." (PMID 38239198, 2023). "Results from related animal models of arthritis also confirmed the importance of TNF in RA." (PMID 36816744, 2023). "These suggest that TNF-α-secreting T cells may be therapeutic targets for intervention of ICI-related arthritis and pneumonitis." (PMID 36016934, 2022).
Arthritis (continued). "IL-23 has been recognized as a potent inflammatory cytokine and mediates arthritis progression by promoting the differentiation and maintenance of Th17 cells in conjunction with the release of IL-17, TNF, and IL-6 from Th17 cells, neutrophils, myeloid cells, and RA FLSs." (PMID 36077117, 2022). "Importantly, blocking TNF-α alleviated arthritis and greatly reduced the expression levels of inflammatory genes." (PMID 34901991, 2022). "In this study, we attempted to establish a mouse model of ICI-related arthritis and pneumonitis in humanized BABL/c-hPD-1/hCTLA4 transgenic mice and characterized their pathogenesis as well as tested the therapeutic effect of anti-TNF-α on ICI-related arthritis and pneumonitis in mice." (PMID 36016934, 2022). "In contrast, we previously identified a requirement for PAD2 in TNF-induced arthritis severity." (PMID 35083342, 2022). "In line with our results, no detectable changes in the trabecular and cortical bone parameters, as assessed by micro-CT, were shown to be at the bone sites far from the inflamed joints after Ang II administration for four weeks in male mice with Tumor Necrosis Factor-mediated arthritis." (PMID 36428495, 2022). "Likewise, D-carvone presented anti-arthritic activity against complete Freund’s adjuvant-induced arthritis in rats via significantly modulating the levels of inflammatory cytokines (IL-6, IL-1β, and TNF-α)." (PMID 36294936, 2022). "With the successful application in this patient, anti-TNF therapy may be a new therapeutic direction for the treatment of patients with HIV combined with other arthritis, which needs to be supported by more data." (PMID 35990692, 2022). "TNF-α inhibitors etanercept, adalimumab, and infliximab are commonly used to treat arthritis." (PMID 36015362, 2022). "Notably, neutralization of TNF in various murine models of arthritis (e.g., CIA, AIA, and arthritis) can rapidly reduce pain and allergic reactions caused by inflammation, in the absence of other analgesics." (PMID 35897734, 2022). "Data from mice with TNF-α induced arthritis showed that TNF-α could stimulate the proliferation and/or differentiation of osteoclast precursors." (PMID 36428337, 2022). "In addition, adjuvants can also induce different immune cells in the knee joint cavity of arthritis to secrete a large number of cytokines (such as TNF-α, IL-1 β and IL-6) and chemokines (including MCP-1, MIP-1α, and RANTES)." (PMID 35572409, 2022). "Our findings suggest that TNF-α+ T cells may be crucial for the pathogenesis of ICI-related arthritis and pneumonitis, and therapeutic targets for intervention of these irAEs." (PMID 36016934, 2022). "In vivo, BHA alleviated paw and joint swelling, decreased inflammatory cell infiltration in paw tissues, suppressed gene expressions of p38 and p65, down-regulated the NF-κB and MAPK signaling pathways and reduced protein levels of TNFα, IL-1β and IL-6 in joint tissues of arthritis rats." (PMID 35630747, 2022). "While joint-draining TNF-Tg popliteal lymphatic vessels (PLVs) have deficits in contractility during end-stage arthritis, the nature of lymphatic muscle cells (LMCs) and their TNF-altered transcriptome remain unknown." (PMID 35255954, 2022). "Treatment with TNF-inhibitors (TNF-i) is more promising in improving arthritis, enthesitis, dactylitis and skin, and presents a better efficacy in preventing joint destruction and radiographic progression with respect to therapy with conventional synthetic DMARDs." (PMID 35887591, 2022). "Based on our experiences in this study, although TNF-α inhibitors effectively reduced mild manifestations such as fever and rash, they were not effective for improving more serious complications like papilledema and arthritis." (PMID 35281325, 2022). "So, we chose MAECs with TNF-α treatment to mimic the microenvironment at the site of arthritis." (PMID 35295653, 2022).
Arthritis (continued). "Moreover, TRAPS mutations strongly suppressed the development of TNFα-mediated arthritis when crossed with human TNFα transgenic mice." (PMID 35936010, 2022). "Importantly, the genomic and transcriptomic responses of the FLS from TNF-driven arthritis mouse model are largely comparable to the responses FLS from human RA patients." (PMID 35529852, 2022). "Spontaneous arthritis in mice expressing a human tumor necrosis factor (hTNF) transgene." (PMID 36387416, 2022). "Collectively, penfluridol was effective in treatment of TNFα-dominant arthritis." (PMID 35045889, 2022). "It was stated that the cytokines such as TNF-α, IL-1β, IL-6, IL-8, and IL-18 secreted by B lymphocytes and synovial fibroblasts (SFs) potentially regulate the balance of anti-inflammatory and pro-inflammatory factors during arthritis." (PMID 35877372, 2022). "In addition, MIF inhibitors can inhibit the activation of macrophages and the expression of inflammatory factors, such as NO, TNF-α and IL-6, which can significantly improve arthritis and articular cartilage injury in rats." (PMID 35395782, 2022). "7-HF has been found to inhibit lipopolysaccharides-induced inflammation via attenuating the production of NO, prostaglandin E2, PGE2, tumor necrosis factor α, TNF-α, and interleukin 6, IL-6, which are mediators in the inflammatory processes accompanying several diseases such as arthritis." (PMID 36559299, 2022). "In order to observe the therapeutic effect of HGWD on arthritis in TNF-Tg mice, we used HE staining to stain the right ankle joints of mice after 8 weeks of intragastric administration of HGWD and quantified the area of inflammation in the ankle joint synovium." (PMID 35600883, 2022). "Uncontrolled activity of S100A8/A9 alarmins drives TNF-induced arthritis in mice." (PMID 35543413, 2022). "Although TNF-α inhibitor treatment has shown improved therapeutic outcomes in various types of arthritis, the injection delivery of biological drugs will lead to increasing the risk of infection and decreasing patient dependency, which sets a barrier to the long-term delivery of TNF-α inhibitors." (PMID 36015362, 2022). "Similarly, cryptotanshinone can reduce the severity of collagen-induced arthritis by inhibiting the production of TNF-α and downregulating the production and activity of matrix metalloproteinase-9." (PMID 36147634, 2022). "First, despite TNF is one of the predominant cytokines in arthritis, there might be other pro-inflammatory cytokines upregulated as part of the cytokine response." (PMID 36307458, 2022). "However other studies indicated that in a mouse model of collagen-induced arthritis, adiponectin significantly reduced the severity of arthritis along with decreasing the expression of TNF-α, IL-1, and MMP-3 in joint tissues." (PMID 35628866, 2022). "Further, we tested whether penfluridol had treatment effect to prevent disease progression in the TNFα-dominant arthritis." (PMID 35045889, 2022). "Altogether, these findings both validate and identify the transcriptional changes in TNF-Tg LMCs, which may be related to the progression of arthritis via various mechanisms." (PMID 35255954, 2022). "Similarly, the release of pro-inflammatory cytokines such as tumor necrosis factor-α (TNF-α), interleukin (IL)-1, and matrix metalloproteinase (MMP) enzymes such as MMP-2, -3, and -9 cause cartilage and joint deterioration in arthritis." (PMID 36293500, 2022). "Some studies have indicated that inhibition of MIF suppresses the activation of macrophages and the expression of inflammatory factors, such as NO, tumor necrosis factor-alpha (TNF-α), and IL-6, thereby decreasing inflammatory responses and ameliorating arthritis and articular cartilage injury." (PMID 36248361, 2022).
Arthritis (continued). "Taken together, IL-17 is a critical pro-nociceptive cytokine in mBSA-induced arthritis through the promotion of neutrophil migration and production of various pro-inflammatory mediators, such as TNF-α, IL-1β, CXCR1/2 chemokine ligands, MMPs, endothelins, prostaglandins, and sympathetic amines." (PMID 36248896, 2022). "Pro-inflammatory cytokines, including interleukin (IL)-6, IL-8, IL-15, IL-17, IL-18, IL-21, IL-1β, IL-33, and tumor necrosis factor (TNF)-α, and anti-inflammatory cytokines, such as IL-4, IL-10, IL-13, and IL-37, play an important role in the pathogenesis of arthritis." (PMID 35565085, 2022). "Since TNF can drive IL-1β secretion via the NLRP3 inflammasome, the role of PAD2 in TNF-induced arthritis may be macrophage-dependent." (PMID 35083342, 2022). "In three articles, homogeneous doses of extracts (10–50 mg/kg) were shown to decrease the arthritis score; the mechanisms that explain the biological effects include the inhibition of pro-inflammatory cytokines (IL-6, TNF-α) and the increase of antioxidant enzymes (MDA, GSH, SOD)." (PMID 36364420, 2022). "The functionally redundant activities of Sox4, Sox11 and Sox12 in TNF-induced arthritis and the diverse range of stimuli that can potentially activate the canonical NF-κB signaling in the FLS are suggestive of a role for multiple additional co-factors besides SOXC and RELA." (PMID 35529852, 2022). "It was important to determine whether, ozoralizumab is effective in suppressing TNFα-induced arthritis once ADAs have generated after repeated administration of adalimumab." (PMID 35273620, 2022). "Uveitis and arthritis might have similar pathogenesis related to immune cell activation and TNF-a hyperproduction." (PMID 35783325, 2022). "Since TNF-α is involved in the differentiation of MDSCs and the pathological process of arthritis, we speculate that MBL may be involved in the process of MDSCs differentiation caused by TNF-α." (PMID 35280697, 2022). "In addition, the frequency of MDSCs, G-MDSCs, and M-MDSCs were similar between WT and MBL-/- arthritis mice after blocking TNF-α." (PMID 35280697, 2022). "Additionally, they were found to directly promote the development of arthritis in mice and to highly stimulate the production of TNF by macrophages." (PMID 36059838, 2022). "Interestingly, upstream regulator analysis identified TNF (p = 2.34 × 10-36), TGFB1(p = 9.02 × 10-36) and IL-1B (p = 2.39 × 10-32) as known senescence and arthritis associated regulators of DEG miRNAs." (PMID 36213127, 2022). "Interestingly only resolving arthritis FLS showed a significant upregulation of glycolysis in response to TNFα." (PMID 34512657, 2021). "Arthritis manifests with the elevation of pro-inflammatory cytokines such as IL-1, IL-6, and TNF-α." (PMID 33478498, 2021). "Aiming at a better definition and understanding of the mode of action of the combination therapy, we made use of a recently published transcriptomic analysis framework and the respective gene expression and function-based profiles of the TNF-dependent arthritis pathology." (PMID 33892739, 2021). "Anti-TNF treatment was also able to abrogate arthritis induced by antibiotic-killed S. aureus." (PMID 33546401, 2021). "Moreover, our preliminary study verified the cytokines (TNF-α, IL-1β) and inflammatory mediators (MMP-1, MMP-3) associated with joint inflammation in animal models." (PMID 34190191, 2021). "In addition, rebamipide, a drug for treatment of UC, also attenuates the inflammation in arthritis and gut by rebalancing the Treg/Th17 cells, suppressing TNF-α, IL-17 level and modulating splenic STAT3 activity." (PMID 33967779, 2021). "In our rat RA model, we also found that anti-TNF treatment could significantly suppress the inflammation in early arthritis." (PMID 33846342, 2021). "Arthritis mice also showed higher levels of TNF-α and IL-17A in the sera." (PMID 34290703, 2021).
Arthritis (continued). "In addition, brucine, strychine and triptolide significantly inhibited the expression of arthritis-related inflammatory factors (i.e., TNF-α, IL-6, COX-2, and iNOS)." (PMID 34108880, 2021). "However, FLS from patients with resolving arthritis showed increased mitochondrial linearity following TNFα treatment in comparison to the other groups." (PMID 34512657, 2021). "Targeted therapies, such as TNF-α inhibitors may be beneficial for secondary CVD4,11,32–35 and OP8,35–38 associated with arthritis." (PMID 34593938, 2021). "The level of TNF-alpha decreased significantly only in the group with arthritis at inclusion; MCP-1 decreased significantly in both the group with arthritis and the whole group, but the decrease did not remain significant after adjustment for multiple comparisons." (PMID 34112181, 2021). "Although anti-TNFα therapies offer a powerful way to manage the progression and treatment of IBD, they are expensive, ineffective in more than 50% of patients, and increase the risk of infections, liver problems, arthritis, and lymphoma." (PMID 34679598, 2021). "In addition, in the interdisciplinary approach of coexisting inflammatory diseases, such as inflammatory bowel disease, hidradenitis suppurativa, or arthritis, TNF-α inhibitors still have a prominent position." (PMID 34834435, 2021). "In addition, -1Ala-TIMP-3 and T2G-TIMP-3 were able to inhibit the aggrecanases (ADAMTS-4 and -5) and block aggrecan degradation, which is, together with TNF release, a key feature of arthritis." (PMID 33579029, 2021). "Treatment with L. casei or L. acidophilus over a period of 28 days reportedly prevented the development of arthritis in a preclinical model that reduced arthritic scores and proinflammatory cytokines such as IL-17, IL-1β, IL-6, and TNF-α, similar to that of indomethacin treatment." (PMID 34065638, 2021). "Moreover, aside from its soluble form, as a transmembrane protein, TNFα on both Mφs and fibroblasts has been shown to induce arthritis in transgenic mice." (PMID 34360720, 2021). "Arthritis improved in five of the seven children with arthritis; in those seven, multiplex analyses showed a significant decrease in nine inflammatory proteins, including TNF-alpha (p = 0.028), after four weeks." (PMID 34112181, 2021). "In this regard, we have previously showed that the human Tumor Necrosis Factor (huTNF) Tg197 arthritis mouse model, in parallel to its RA pathology, also develops TNF-driven VHD, which mainly leads to valvular thickening with some degree of stenosis and occasionally insufficiency." (PMID 34884213, 2021). "In vivo, the effect of PS VII on the weight of the rat, paw swelling, ankle joint diameter, arthritis index, serum inflammatory cytokines (TNF-α, IL-6, and IL-1β), histopathological assessment and apoptosis proteins in the synovial tissues were evaluated in AIA rats." (PMID 34122110, 2021). "Moreover, patients with arthritis who received anti-inflammatory anti-TNF-α treatments with methotrexate or infliximab developed VL, which was further successfully cured with LAMB." (PMID 34777391, 2021). "Anti-TNF-α therapies are effective in reducing inflammation and the progression of radiologic damage in RA patients and in murine models of arthritis, however, the mechanism by which TNF-α inhibitors (TNFαI) prevent the progression of bone destruction is still unclear." (PMID 34209821, 2021). "Similarly, treatment with TNFα inhibitors showed transient but un-sustained improvement in sJIA arthritis, its role in controlling fever and other systemic signs has been unsuccessful." (PMID 33996701, 2021). "LMT-28 could alleviate arthritis and acute pancreatitis in mice, reduce the secretion of TNF-α in serum, and inhibit IL-6-induced phosphorylation of Stat3, gp130 and JAK2 proteins." (PMID 34955842, 2021).